IQUB (IQ motif and ubiquitin domain containing)
Description:
Adapter protein that anchors the radial spoke 1 (RS1) complex to the A microtubule of outer doublet microtubules in axonemes. The triple radial spokes (RS1, RS2 and RS3) are required to modulate beating of the sperm flagellum. May play a role in inhibiting signaling via MAPK1/ERK2 and MAPK3/ERK1. Additionally, may play a role in the functioning of cilia (By similarity). Not required for the functioning of tracheal or ependymal cilia (By similarity).
Synonyms: FLJ35834; TRS4
Tractability: Small molecule: a structure with a bound ligand is known.
Gene: Protein-coding gene on chromosome 7 (123,452,174 to 123,535,077, reverse strand). Ensembl gene ENSG00000164675.
Subcellular location: Cytoplasm, cytoskeleton, flagellum axoneme; Cell projection, cilium
Subcellular location (Human Protein Atlas): End piece; Mid piece; Nuclear speckles; Principal piece; Cytosol; Nucleoplasm
Gene Ontology:
Molecular function: protein binding
Biological process: flagellated sperm motility; mating; cilium assembly
Cellular component: 9+2 motile cilium; acrosomal vesicle; motile cilium; radial spoke; sperm flagellum; cilium
Genetic constraint (gnomAD): Loss-of-function variants: 55 observed, 56.9 expected, observed/expected ratio (o/e) 0.97, 90% interval 0.78 to 1.21. The upper end of that interval is the gene's LOEUF score, 1.21, which puts it in group 5 of 6, group 1 being the genes least tolerant of losing a copy. Missense variants: 664 observed, 663.66 expected, observed/expected ratio (o/e) 1, 90% interval 0.94 to 1.07. Synonymous variants: 207 observed, 225.73 expected, observed/expected ratio (o/e) 0.92, 90% interval 0.82 to 1.03.
Homologues: Orthologues: chimpanzee IQUB (99% identical), macaque IQUB (95% identical), pig IQUB (77% identical), rabbit IQUB (75% identical), guinea pig IQUB (74% identical), mouse Iqub (69% identical), rat Iqub (69% identical), dog IQUB (69% identical), tropical clawed frog iqub (48% identical), zebrafish iqub (42% identical), Drosophila melanogaster CG13855 (25% identical).
Diseases named in the same sentence as IQUB in open-access papers:
IQUB is named in the same sentence as 10 diseases in open-access papers, as found by Europe PMC text mining. Sharing a sentence is not in itself a finding about the gene and the disease. The quoted sentences say what the papers report.
gastric cancer (2 papers, 2015 to 2018). A primary or metastatic malignant neoplasm involving the stomach. "Only one tumor‐related study referred to IQUB which found that IQUB was upregulated in gastric cancer tissues by transcriptome sequencing, but the mechanism was not clear." (PMID 29968965, 2018).
male infertility (2 papers, 2025 to 2026). The inability of the male to effect fertilization of an ovum after a specified period of unprotected intercourse. "The exception is the RS1 base protein, CFAP253/IQUB, whose mutation also causes male infertility but not PCD." (PMID 40886204, 2025). "Research on the epidemiological links between IQ motif family genes (IQUB, IQCN, IQCH) and male infertility, while establishing initial genotype-phenotype correlations, is constrained by significant limitations that affect the generalizability and depth of conclusions for each gene." (PMID 41602861, 2026).
asthenozoospermia (1 paper, 2026). "Pathogenic variants such as the homozygous IQUB c.942T > G mutation are linked to asthenozoospermia, while loss-of-function IQCN mutations cause total fertilization failure." (PMID 41602861, 2026). "Specific loss-of-function mutations are strongly linked to distinct clinical phenotypes: IQUB variants to asthenozoospermia, IQCN mutations to total fertilization failure, and IQCH deficiency to azoospermia." (PMID 41602861, 2026). "For IQUB, the pathogenic c.942T > G variant has been robustly linked to asthenozoospermia but only within a specific Chinese Han cohort." (PMID 41602861, 2026). "Within the subset of cases with a genetic etiology, mutations in specific IQ motif genes have been established as monogenic causes for distinct phenotypes: IQUB (c.942T > G) with asthenozoospermia, IQCN (c.1061_1062delAT) with total fertilization failure, and IQCH variants with azoospermia." (PMID 41602861, 2026). "In East Asians, the IQUB c.942T > G mutation is exclusive to Han Chinese asthenozoospermia patients (0.8% frequency), absent in Japanese/Korean cohorts, and disrupts sperm flagellar radial spoke assembly." (PMID 41602861, 2026). "Whole-exome sequencing of 126 Chinese Han patients with asthenozoospermia identified a homozygous nonsense mutation (c.942T > G, p.Tyr314*) in the IQUB gene, which was absent in healthy controls." (PMID 41602861, 2026).
breast carcinoma (1 paper, 2018). "In vitro study, the biological functions of IQUB in breast cancer cells were detected by gain‐ and loss‐of‐expression strategy." (PMID 29968965, 2018). "Therefore, we examined the association between IQUB and Wnt/β‐catenin signaling pathway in breast cancer cells." (PMID 29968965, 2018). "Further study showed that IQUB expression was significantly increased in breast cancer, which had a significantly positive correlation with pathological differentiation of breast cancer by tissue microarray analysis." (PMID 29968965, 2018). "Our previous study found that the expression of IQUB (IQ motif and ubiquitin domain containing) was significantly increased in the development of breast cancer by transcriptome sequencing." (PMID 29968965, 2018). "In conclusion, our results indicated that the expression of IQUB was increased in breast cancer and positively correlated with malignancy of breast cancer for the first time." (PMID 29968965, 2018). "In conclusion, our study indicated that IQUB promoted the proliferation and migration of breast cancer cells via activating Wnt/β‐catenin signaling pathway." (PMID 29968965, 2018). "To investigate the expression of IQUB protein between normal breast tissues and breast cancer tissues, we examined breast cancer tissue microarray, which included 100 cases of breast cancer tissues by immunohistochemistry." (PMID 29968965, 2018). "Taken together, these results indicated that upregulated IQUB promoted breast cancer cell proliferation and migration via activating Akt/GSK3β/β‐catenin signaling pathway, which played an important part in the tumorigenesis and development of breast cancer." (PMID 29968965, 2018). "Then, we detected IQUB mRNA expression in 20 pairs of breast cancer tissues and adjacent normal tissues by RT‐qPCR." (PMID 29968965, 2018). "The result indicated that compared to adjacent tissues, the expression of IQUB mRNA was significantly increased in 16 cases of breast cancer tissues (P < .05)." (PMID 29968965, 2018). "Furthermore, IQUB overexpression or knockdown combined with treatment of Licl or MG‐132 showed that IQUB activated Akt to promote GSK3β phosphorylation, which in turn activated Wnt/β‐catenin signaling pathway in breast cancer cells." (PMID 29968965, 2018). "In addition, we further explored the mechanism of IQUB in promoting breast cancer by activating the Akt/GSK3β/β‐catenin signaling pathway, which would provide a new idea for better comprehension of breast cancer pathogenesis and breast cancer targeted therapy." (PMID 29968965, 2018). "According to these results, overexpression of IQUB could significantly promote migration of breast cancer cells." (PMID 29968965, 2018). "IQUB could activate Akt/GSK3β/β‐catenin signaling pathway, promoting proliferation and migration of breast cancer cells." (PMID 29968965, 2018). "In vitro study, overexpression of IQUB could significantly enhance the proliferation and migration ability of breast cancer cells, whereas knockdown of IQUB showed the opposite effect." (PMID 29968965, 2018). "Combined with our transcriptome sequencing in breast cancer, we speculated that IQUB may act an important role in the development of tumor." (PMID 29968965, 2018). "In this study, we firstly sought to probe the role of IQUB in breast cancer." (PMID 29968965, 2018). "In addition, we also found that MK2206 could significantly inhibit the effect of IQUB overexpression on promoting proliferation and migration of breast cancer cells by clone formation assay and Wound healing assay." (PMID 29968965, 2018). "In our previous work, we found that IQUB (IQ motif and ubiquitin domain containing) had apparently higher expression in breast cancer than that in normal tissues, suggesting that it may act an important role in the occurrence and development of breast cancer." (PMID 29968965, 2018).
breast carcinoma (continued). "Finally, we found that MK2206 also reversed the effect of IQUB overexpression on breast cancer cells by clone formation assay and Wound healing assay, which indicated that IQUB could promote proliferation and migration of breast cancer cells through activating Akt/GSK3β/β‐catenin signaling pathway." (PMID 29968965, 2018). "Furthermore, it was found by flow cytometry that IQUB overexpression induced G1/S transition in MCF‐7 cells, while IQUB knockdown decreased proportion of MDA‐MB‐231 cells in S/G2 phase, suggesting that IQUB could promote proliferation of breast cancer cells by accelerating G1/S transition." (PMID 29968965, 2018). "To test the effect of IQUB on cell migration, we transfected IQUB overexpression plasmid flag‐IQUB and negative control flag‐NC, small interfering RNA of IQUB siR‐IQUB and negative control siR‐NC into breast cancer cells." (PMID 29968965, 2018).
type 2 diabetes (1 paper, 2022). "Using pharmacophore target analysis in a network pharmacology approach, we identified five potential target genes for celastrol in the treatment of type 2 diabetes, including RBP3, BMP7, S100A11, HBB and IQUB." (PMID 36339449, 2022).
cancer (3 papers, 2015 to 2019). A tumor composed of atypical neoplastic, often pleomorphic cells that invade other tissues. "Furthermore, it has been shown in a cancer research that knockdown of IQUB gene can prevent c-myc expression (c-myc is a muscle regulator gene which is involved with proliferation and differentiation of muscle myoblast)." (PMID 31600309, 2019).
IQUB also shares sentences with these, for which no sentence is quoted: Azoospermia (1 paper); chronic gastritis (1); metastatic cancer (1); tumor (1).